METTL14 (methyltransferase 14, N6-adenosine-methyltransferase non-catalytic subunit)
Diseases named in the same sentence as METTL14 in open-access papers (continued):
Sharing a sentence is not in itself a finding about the gene and the disease.
glioma (29 papers, 2016 to 2025). A benign or malignant brain and spinal cord tumor that arises from glial cells (astrocytes, oligodendrocytes, ependymal cells). "Associations between glioma malignancy grade and the expression of m6 A writers (METTL3, METTL14, WTAP, and RBM15), the reader YTHDF, and erasers (ALKBH5 and FTO) are shown." (PMID 40382536, 2025). "IGF2BP3 downregulated the expression of both m6A-associated writers (METTL3, METTL14) and erasers (FTO, ALKBH5), with a specific focus on FTO due to its more pronounced effect in both U87MG and GL261 glioma cell lines." (PMID 38167409, 2024). "MRE11, RTCB, TIMM9 and METTL14 were up‐regulated in gliomas, while CDPIT and MFN2 were down‐regulated." (PMID 35044082, 2022). "Subsequently, the differential analysis showed that, between glioma and normal brain tissue, a variety of m6A-related genes were differentially expressed, including METTL14, METTL16, ZC3H13, YTHDC1, YTHDC2, YTHDF2 etc." (PMID 35559019, 2022). "Additionally, the expression of ADAM19 is increased after METTL14 knockdown, which promotes the occurrence of glioma." (PMID 40469294, 2025). "Interestingly, compared to METTL3, METTL14 demonstrates more pronounced effects and primarily acts as an inhibitor of glioma progression, offering a novel avenue for therapeutic interventions in this disease." (PMID 37964279, 2023). "The significant overlapping pathways between METTL3 and METTL14 include Glioma (20 mDrGenes in KD-METTL3, pBonferroni = 1.37×10−6, 13 mDrGenes in KD-METTL14, pBonferroni = 1.85×10−3), suggesting that these mDrGenes may be used as biomarkers of glioma." (PMID 28027310, 2016). "The results showed that METTL14, FTO, YTHDF1, and YTHDF3 demonstrated significant upregulation in low-grade gliomas compared to normal tissues." (PMID 38398118, 2024). "In glioma stem-like cells, METTL3 and METTL14 were also shown to suppress cell differentiation, while WTAP and ALKBH5 promote cell proliferation, self-renewal, and tumorigenicity." (PMID 36293529, 2022). "We decreased VPS25 expression in METTL3, METTL14, and YTHDC1 KD glioma cells, and a series of restoration assays were performed." (PMID 34863175, 2021). "METTL14 has been reported as a tumor suppressor gene in GBM, and the erasers FTO and ALKBH5 are oncogenes in glioma." (PMID 33134160, 2020). "The expression of WTAP was also significantly correlated with the ‘writers’ of METTL14, KIAA1429 and RBM15 in gliomas." (PMID 30810537, 2019). "In glioma cells, downregulation of METTL14 induces down-regulation of m6A modification and expression of circRNA_103239, driving up-regulation of miR-182-5p and down-regulation of MTSS1, thereby promoting EMT in glioma and promoting tumor progression." (PMID 41256854, 2025). "In addition to WTAP, the expression of METTL14, RBM15, and its paralogue RBM15B is also increased in gliomas." (PMID 40469294, 2025). "According to these findings, RP2 may be correlated with m6A modification in glioma, and the combined effect of METTL14, VIRMA, ALKBH5, YTHDC2 and METTL3 may eventually affect the progression and poor prognosis of glioma." (PMID 37602882, 2023). "The m6A quantitative analysis showed that the METTL3 and METTL14 KD decreased the total m6A modification level in glioma cells, whereas the YTHDC1 KD did not." (PMID 34863175, 2021). "The mRNA level of VPS25 was upregulated in glioma cells with KD of METTL3 or METTL14, but it was not affected in the YTHDC1 KD cells." (PMID 34863175, 2021). "We then speculated that METTL3, METTL14, and YTHDC1 might affect the proliferation of glioma cells through VPS25." (PMID 34863175, 2021). "As is visible in the violin plot, the mRNA expression levels of YTHDF2, YTHDF1, METTL3, RBM15 and HNRNPC were up‐regulated in glioma compared to normal tissues, whereas the expression levels of ALKBH5, WTAP, YTHDC2, ZC3H13 and METTL14, especially of FTO, were decreased in glioma." (PMID 32449290, 2020).
glioma (continued). "We noticed that the expression of both METTL3 and METTL14 were not correlated with the WHO grade of gliomas." (PMID 30810537, 2019). "However, the protein level of VPS25 was not affected in glioma cells with KD of METTL3 or METTL14, but it was upregulated in the YTHDC1 KD cells." (PMID 34863175, 2021). "METTL14 did not stratify survival of gliomas in either RNA-seq or Microarray cohorts." (PMID 34246306, 2021).
liver cancer (28 papers, 2018 to 2025). An epithelial or non-epithelial malignant neoplasm that arises from the liver. "This, in turn, reduces the effectiveness of immune checkpoint inhibitors, such as anti-PD-1 and anti-PD-L1 antibodies, highlighting METTL14’s central role in immune resistance in liver cancer." (PMID 39911396, 2025). "METTL14 mediates lncRNA RP1-228H13.5 to promote the development of liver cancer through targeting hsa-miR-205 and regulating the expression of zinc finger protein interacting with K protein 1 (ZIK1)." (PMID 41256854, 2025). "By increasing PD-L1 expression on the surface of liver cancer cells, METTL14 dampens the immune response by inhibiting the activation of effector T cells." (PMID 39911396, 2025). "Conversely, in liver cancer, METTL14 impeded the invasion and metastasis of cancer cells by regulating miR-126." (PMID 39054337, 2024). "When we performed survival analysis using METTL3 and METTL14 as a gene set, we found that METTL3 and METTL14 contributed completely opposite prognostic risk values in liver cancer." (PMID 38965238, 2024). "Given that the important role of hypoxia in tumor development, our research group has long focused on the role of hypoxia in liver cancer, and METTL3 YTHDF2 and METTL14 has been studied more frequently in liver cancer." (PMID 35982895, 2022). "METTL14 plays a tumor-suppressing effect in liver cancer and is the only m6A modifier that suppresses liver cancer tumorigenesis." (PMID 35945641, 2022). "For example, METTL14 was originally considered as a tumor suppressor in liver cancer; METTL14 induced the increased expression of pri-miR-126, which inhibited tumor metastasis." (PMID 36360287, 2022). "In liver cancer, changes in the m6A levels are caused by increased METTL3 and/or METTL14 expression." (PMID 35155557, 2022). "Except for METTL16 and METTL14, the m6A writers are upregulated in liver cancer tissues and act as oncogenes." (PMID 34692544, 2021). "Studies have reported an opposing trend in the expression of METTL3 and METTL14 in patients with liver cancer." (PMID 32307908, 2020). "In HCC, especially in metastatic HCC, it has been shown that the expression of METTL14 in tumor cells and tissues were reduced, which is closely related to the poor prognosis of liver cancer." (PMID 33292652, 2020). "In liver cancer, multiple different groups’ investigations showed that METTL14 inhibits EMT, invasion and metastasis of liver cancer cells by regulating m6A-modified target mRNAs such as EGFR/PI3K/AKT, DGCR8/primiR-126, USP48/SIRT6/glycolysis, CSAD, GOT2 and SOCS2." (PMID 40734692, 2025). "Targeting METTL14 represents a promising strategy for enhancing liver cancer immunotherapy." (PMID 39911396, 2025). "In addition to ZC3H13 and METTL14, m6A writers have been shown to be oncogenic factors in liver cancer." (PMID 39967906, 2025). "METTL14, a critical component of the m6A RNA methyltransferase complex, plays a pivotal role in regulating the initiation, progression, and modulation of the immune microenvironment in liver cancer." (PMID 39911396, 2025). "METTL14 can inhibit liver cancer metastasis in an m6A‐dependent manner by increasing miR126 levels." (PMID 38613157, 2024). "As a tumor suppressor gene, miR126 is a target gene of METTL14 in liver cancer metastasis." (PMID 33292652, 2020). "In contrast, m6A writers METTL14 and ZC3H13 inhibit liver cancer progression." (PMID 39967906, 2025). "First, our analysis of gene set enrichment analysis (GSEA) using The Cancer Genome Atlas (TCGA) Liver Hepatocellular Carcinoma (LIHC) data revealed a negative correlation between METTL14 and the regulation of liver cancer stemness." (PMID 40290127, 2025). "Analogous to METTL14, WTAP upregulation in HCC promoted liver cancer development." (PMID 35806168, 2022). "In liver cancer, METTL3 and METTL14 play opposite roles in tumor development." (PMID 34489709, 2021).
liver cancer (continued). "However, the critical m6A writers (METTL3, METTL14) were also reported to serve as tumor suppressor in GBM and liver cancer 19,20." (PMID 32284755, 2020).
renal cell carcinoma (25 papers, 2020 to 2025). "They established a risk signature for predicting the prognosis of renal cell carcinoma based on METTL14 and METTL3." (PMID 32808488, 2020). "Notably, METTL14 deficiency was found to promote the metastasis of renal cell carcinoma in both in vivo and in vitro experiments." (PMID 39759516, 2024). "METTL14 deficiency in renal cell carcinoma (RCC) promotes distal lung metastasis by enhancing glycolytic reprogramming." (PMID 36859310, 2023). "METTL14 expression is attenuated in renal cell carcinoma tissues, and ectopic overexpression of METTL14 inhibits cell proliferative capacity and invasive migration potential." (PMID 40986143, 2025). "For instance, the m6A methylase METTL14 was reported to negatively regulate the expression of SRC in renal cell carcinoma." (PMID 40612868, 2025). "The expression level of METTL14 in renal cell carcinoma (RCC) is lower than that in normal tissues, and down-regulation of METTL14 expression predicts poor prognosis of renal cell carcinoma." (PMID 39289775, 2024). "In renal cell carcinoma, METTL14 is regulated by the competitive binding effect of circRNAs and miRNAs, and affects the expression of downstream molecule PTEN and changes in related AKT/PKB signals." (PMID 34904301, 2022). "Our results discovered that high METTL14 expression had association with ERBB pathway, MAPK pathway, mTOR pathway, renal cell carcinoma, TGF-β pathway and Wnt pathway by GSEA." (PMID 33430867, 2021). "Decreased METTL14 and increased carcinogenesis in renal cell carcinoma (RCC) has been reported in a recent study." (PMID 33814008, 2021). "A similar METTL14 expression pattern was found in renal cell carcinoma, and METTL14 further suppressed P2RX6 activation regulated metastasis of renal cell carcinoma via ATP‐induced Ca2+ influx modulating ERK1/2 phosphorylation and MMP9 signalling." (PMID 32808488, 2020). "Notably, in renal cell carcinoma, METTL14 and IGF2BP2 collaboratively regulate tumor angiogenesis and metastasis while also managing drug resistance in cancer cells during clinical treatment." (PMID 39295872, 2024). "Low METTL3 expression in renal cell carcinoma (RCC) suggests a tumor suppressor role, while reduced METTL14 expression weakens m6A modification on tumor suppressor transcripts (e.g. BPTF and PTEN), thereby promoting cancer cell invasion and metastasis." (PMID 41446042, 2025). "METTL14 regulates m6A modification of lncRNA–NEAT1_1, affecting renal cell carcinoma (RCC) cell migration." (PMID 39802639, 2025). "Consequently, we hypothesize that the development of METTL14-targeted inhibitors could have a substantial impact on the clinical management of renal cell carcinoma, paving the way for new therapeutic approaches." (PMID 39295872, 2024). "In addition, down‐regulation of METTL14 in renal cell carcinoma was related to poor prognosis, and that METTL14 regulated PTEN expression via m6A modification, which indicated that METTL14 could possibly serve as a prognostic biomarker." (PMID 32808488, 2020). "In renal cell carcinoma (RCC), METTL14 downregulates the expression of bromodomain PHD finger transcription factor (BPTF) to attenuate the oncogenic transcriptome, glycolytic reprogramming, and distal lung metastasis." (PMID 38721006, 2024). "However, in the tissues of renal cell carcinoma (RCC), METTL14 regulates the expression of NEAT1 through another recognition protein YTHDF2." (PMID 38654314, 2024). "Downregulated METTL14 in RCC promotes proliferation and migration of renal cell carcinoma cells by inhibiting PTEN expression through M6A modification." (PMID 37865763, 2023). "recently investigated the vital role of m6A modification and the METTL14/BPTF axis in the epigenetic and metabolic remodeling of metastasis of renal cell carcinoma, highlighting the BPTF inhibitor-AU1 as a key therapeutic candidate." (PMID 36505780, 2022).
renal cell carcinoma (continued). "Further study has shown that METTL3, along with METTL4, METTL14, NCBP1, and WTAP, may interact to impact cell cycle, renal cell carcinoma, and pathways that are included in cancer and hence may influence CRC growth." (PMID 40177651, 2025). "In contrast, both m6A methyltransferases (METTL3 and METTL14) and m6A demethylases (FTO) act as tumour suppressor genes in renal cell carcinoma, indicating that the recruited m6A‐binding protein and potential downstream target play important roles in tumour development." (PMID 32808488, 2020). "METTL14 exerts an oncogenic effect in HCC and AML, but suppresses tumor progression in CRC and renal cell carcinoma (RCC)." (PMID 39098905, 2024).
lung carcinoma (23 papers, 2020 to 2025). "For example, METTL14 expression in lung cancer is higher than that in normal lung tissue and is associated with aggressiveness and metastatic ability of the tumor." (PMID 41323393, 2025). "In contrast, IL‐37 upregulates METTL14 expression in lung cancer, thereby enhancing CD8+ T‐cell infiltration." (PMID 41316520, 2025). "Taken together, KCTD10 suppresses lung cancer progression and immune escape via the β-catenin/PD-L1 axis, and its expression is tightly regulated by METTL14-dependent m6A modification, highlighting its potential as a therapeutic target." (PMID 41164187, 2025). "The GEPIA database revealed lower METTL14 expression in lung cancer tissues, and the Kaplan-Meier plotter analysis indicated that high METTL14 expression was associated with improved prognosis." (PMID 40873559, 2025). "In lung cancer, METTL14 stabilizes HSD17B6 mRNA through m6A modification, suppressing CD8+ T-cell infiltration and activation, ultimately facilitating tumor progression and impairing PD-1 blockade efficacy." (PMID 41164187, 2025). "Our findings establish KCTD10 as a critical regulator of both tumor progression and the tumor environment, highlighting the therapeutic potential of the novel METTL14/KCTD10/β-catenin regulatory axis in lung cancer treatment." (PMID 40873559, 2025). "METTL3 oncogenic role has also been reported in lung cancer, where it is overexpressed in human lung cancer tissues compared with normal tissues, and METTL14 protein and transcript abundance are also increased." (PMID 39445003, 2024). "In the present study, we found that high METTL14 expression indicated a poor prognosis in patients with lung cancer." (PMID 38725005, 2024). "These online prediction results indicated that the level of METTL14 was closely related to the survival of lung cancer patients." (PMID 38725005, 2024). "This study aimed to analyze the relationship between METTL14 and the immune checkpoint inhibitor programmed death receptor 1 (PD-1) in lung cancer." (PMID 38725005, 2024). "CCK-8, colony formation, transwell, wound healing, and flow cytometry assays were performed to explore the role of METTL14 in lung cancer progression in vitro." (PMID 38725005, 2024). "The online database GEPIA showed that high METTL14 expression indicated a poor prognosis in patients with lung cancer." (PMID 38725005, 2024). "In conclusion, our study explored the role of METTL14-mediated m6A modification in lung cancer progression and clarified the m6A-dependent regulatory mechanism involved." (PMID 38725005, 2024). "Compared with paired adjacent normal tissues, lung cancer specimens exhibited consistently upregulated METTL14/IGF2BP2/AC026356.1." (PMID 37142269, 2023). "A recent study showed that METTL14 enhances the maturation of miR-30c-1-3p and that miR-30c-1-3p expression inhibits lung cancer malignant transformation." (PMID 37627217, 2023). "In tumor stromal cells, especially TAM, METTL3 or METTL14 can serve as a protective genes for lung cancer." (PMID 35331234, 2022). "The role of METTL14 in lung cancer is controversial; a recent study showed that METTL14 knockdown suppressed the malignant progression of non-small cell lung cancer (NSCLC) by reducing Twist expression." (PMID 36139662, 2022). "And METTL14 overexpression inhibited lung cancer growth and metastasis in vivo and in vitro through the miR-30c-1-3p/MARCKSL1 axis." (PMID 35331234, 2022). "However, methyltransferase-like 14 (METTL14), which serves as the main component of the m6A complex, has been less reported to be involved in the immune microenvironment of lung cancer." (PMID 38725005, 2024). "In addition, the disease-free survival (DFS) of lung cancer patients with high METTL14 expression was lower than that of patients with low METTL14 expression." (PMID 38725005, 2024). "Therefore, the present study aimed to analyze the relationship between the m6A methyltransferase METTL14 and PD-1 in lung cancer." (PMID 38725005, 2024).